MTOR (mechanistic target of rapamycin kinase)
Diseases named in the same sentence as MTOR in open-access papers (continued):
Sharing a sentence is not in itself a finding about the gene and the disease.
cancer (continued). "Regardless of the type of cancer, mTOR is a universal mediator of protein synthesis affecting angiogenesis and proliferation and mechanistically its inhibition may circumvent resistance." (PMID 27501793, 2016). "Since Akt signaling plays a key role in cancer cell proliferation and antiapoptosis, it is reasonable to suggest that mTOR-Akt negative feedback might play an essential role in suppressing the antitumor efficacy of rapamycin in CCA." (PMID 27863431, 2016). "It was reported that mTOR inhibitors have been used to treat several advanced cancers, thus, further investigations are needed regarding whether or not 18α-GA induced cancer cell apoptosis involves AKT/mTOR pathways." (PMID 27376261, 2016). "Cell treatment with 1μM of the dual inhibitor PI3K/MTOR PI-103 for 24 h can trigger autophagic properties, as shown by the induced overexpression of LC3II protein levels, followed by a reduction in p62 protein levels in additional non BRAFV600E cancer cell lines Caco-2, DLD1 and HCT116." (PMID 26802026, 2016). "The mechanisms by which metformin affects cancers are also unknown, although a large number of publications have shown that metformin could exert its antitumor effect by targeting AMPK/mTOR, anti-inflammatory, cell cycle/apoptosis, insulin/IGF-1R, and angiogenesis pathways in cancers." (PMID 27517917, 2016). "We next hypothesized that, since mTORC1 activity is reduced in hypoxic regions, blocking mTOR with rapamycin would not influence cancer cell proliferation in these regions." (PMID 27153561, 2016). "In cancer treatment, statins are believed to serve as prenylation inhibitors of Ras GTPase, which may suppress extensive Ras downstream signalling pathways, such as PI3K/Akt/mTOR and MAPK/ERK." (PMID 26565813, 2016). "Metformin probably influences mitochondria in cancer cells to reduce tumorigenesis, and inhibits both insulin-like growth factor (IGF) signaling and mTOR; it also modulates AMP kinase (AMPK), represses the AKT/mTOR pathway, eliminates cancer stem cells (CSCs) and inhibits tumor growth." (PMID 27577068, 2016). "However, more detailed study of mTOR signaling in response to PGRN is needed, especially in cancer." (PMID 27517315, 2016). "Because the mTOR pathway regulates energy metabolism and as cancer can be regarded as a metabolic disorder, it is not surprising that BMI might be a mediator between mTOR variants and cancer susceptibility." (PMID 27462867, 2016). "Of the remaining articles, 27 studies were ruled out because of the following reason: expression level of mTOR/p-mTOR not measured, no data about HRs but median survival time or 5-year survival rate, no data about OS but cancer specific survival (CSS) or progression free survival (PFS)." (PMID 25680114, 2015). "Interestingly, several studies have shown how rapamycin and its analogs, i.e., allosteric MTOR inhibitors, in combination with autophagy inhibitors (e.g., HCQ, bafilomycin A1, and methyladenine) increased in vitro and in vivo cytotoxicity of human cancers." (PMID 26284195, 2015). "Thus, our studies suggested that first, gal-1 can function both intracellularly and extracellularly, and second, gal-1 might regulate the phenotypes of cancer stem cells through activation of COX-2/PGE2 and Akt/mTOR pathways." (PMID 25605013, 2015). "Additionally, activation of AMPK and PTEN could inhibit mTOR signaling, implying that pAMPK and PTEN function as tumor suppressors in the development of human cancer." (PMID 25909163, 2015). "While mTOR may not be the final molecule responsible for the anti-cancer effect, it remains an attractive target in cells which have lost PTEN since a major effector molecule of pAKT is mTOR." (PMID 26497685, 2015).
cancer (continued). "The PI3K/AKT/mTOR pathway has a critical role in the pathogenesis of HCC, and it has emerged to be an important therapeutic target for anticancer drug development, since many clinical studies have indicated that activation and deregulation of PI3K/Akt pathway play roles in various human cancers." (PMID 26003166, 2015). "Furthermore, the properties of NPC CSCs were studied by treating NPC cells with rapamycin to determine whether inhibition of the mTOR signaling pathway would reduce the number of CD44-positive cells and depress cancer cell proliferation." (PMID 26202311, 2015). "Improvement of our understanding of the mechanism by which the PI3K/Akt/mTOR signalling pathway contributes to the immortalization and carcinogenesis of HPV-transduced cells will assist in devising novel strategies for preventing and treating HPV-induced cancers." (PMID 26022660, 2015). "We thus hypothesized that the lack of beneficial effects needed to lower cancer incidence in some metformin users observed in epidemiological studies could be due to alterations in autophagy and mTOR signaling." (PMID 26111001, 2015). "It was shown that mTOR signal and hypoxia-inducible factor -1α, which was an important factor to induce EMT, regulated CD133 expression in cancer cells, indicating that CD133 expression and EMT phenotypes were related to hypoxia and might be regulated by mTOR signal." (PMID 26284927, 2015). "Further downstream, autophagy may influence the PI3K/AKT/mTOR pathway that is also implicated in OS thus making JCTH-4 a promising agent, although the effect of autophagy in cancers yet is not well characterized." (PMID 26039064, 2015). "The role of the PI3K/Akt/mTOR pathway in the development of resistance to standard anticancer therapy has been a recent focus of research and the inhibitors of the PI3K/AKT/mTOR pathway that restore sensitivity of cancers that have acquired resistance to standard therapy have been discussed." (PMID 25946033, 2015). "Interestingly, loss of SAM68 reduces breast and PCa incidence, suggesting that in cancer cells SAM68 activation may also regulate the expression of PI3K downstream kinases, such as mTOR." (PMID 26273626, 2015). "Thus, the mechanism by which GAPDH inhibits mTOR-p70S6K pathway through E-cadherin is still unknown, but GAPDH is newly rediscovered as an anti-cancer strategy." (PMID 25785838, 2015). "MEK but not mTOR inhibition in vitro induced cytotoxicity, reduced inflammatory cytokine secretion and CD44 expression and reduced migratory capacity in MOC1 and MOC2 cells, consistent with the Ras-driver mutations shared by these carcinomas." (PMID 26506415, 2015). "Second generation mTOR inhibitors that act as ATP-competitive inhibitors of both mTORC1 and mTORC2, or dual specificity inhibitors that target PI3K as well, indirectly suggest a role for mTORC2 in cancer development, possibly by rendering cancer cells more sensitive to replication stress." (PMID 24992933, 2014). "AKT has been shown to promote cancer cell proliferation and survival by diverse mechanisms including the activation of downstream targets including forkhead transcription factors, GSK3, BAD, Bcl-XL, nuclear factor-kB, and mammalian target of rapamycin (mTOR) kinase." (PMID 24968355, 2014). "Taken together, our findings show that Runx2 promotes cancer cell survival by directly inducing subunits of mTORC2 kinase complex of the Akt signaling pathway and further suggest Runx2 inhibition as a potential therapeutic strategy in combination with currently available PI3K/Akt/mTOR inhibitors." (PMID 24479521, 2014). "Controversial recent evidence suggests that statins may both activate or suppress the mTOR pathway in cancer or non-cancer cells." (PMID 24923264, 2014).
cancer (continued). "Most patients with FBXW7 mutations had limited benefit from mTOR based therapies; however, studying mTOR inhibitors in cancers lacking simultaneous molecular abnormalities as well as describing functional consequences of specific FBXW7 mutation subtypes warrants further investigation." (PMID 24586741, 2014). "Previous reports have noted that PP242 inhibition of mTOR may not be sufficient to reduce cell growth of cancer cells because of its ability to trigger compensating signals that activate the AKT pathway." (PMID 25392452, 2014). "The mTOR pathway was constitutively activated in cancer SKBR3 cells even in the absence of serum." (PMID 25587030, 2014). "Therefore, CK1α might provide a therapeutic target for the treatment of cancers characterized by low DEPTOR levels and activation of mTOR signaling, leading to increasing DEPTOR levels, and inhibition of mTOR signaling." (PMID 24904820, 2014). "We hypothesized that during autophagy induced in cancer cells by i) starvation through serum and amino acid deprivation or ii) treatment with PI-103, a class I PI3K/mTOR inhibitor, glycolytic metabolism would be affected, reducing flux to lactate, and that this effect may be reversible." (PMID 24667972, 2014). "Thus, the effectiveness of metformin in reverting early EC to normal endometria might be due to its anti-cancer effects on cellular metabolism and the AMPK and mTOR axis in the endometrium in addition to its systemic effects." (PMID 24887156, 2014). "Moreover, a controversy exists in the literature regarding the use of ALDH+ cells isolated from cancer cell lines as in vitro models for CSC study, further indicating the need to study the effect of mTOR inhibition using alternative methods to identify and characterize CSCs." (PMID 24393708, 2014). "Mammalian target of rapamycin (mTOR), a 289-kDa serine/threonine kinase and a downstream effector of the phosphoinositide 3-kinase (PI3K)/Akt signaling pathway, was identified as a promising therapeutic target for the treatment of a number of types of cancer, including CCA." (PMID 24527093, 2014). "Furthermore, mTOR inhibitors induce Akt activation through an IGF-1R-dependent negative feedback loop in different types of human cancer cell lines, which weakens the anti-tumor effect of mTOR inhibitors." (PMID 25026290, 2014). "Consistent with previous findings in other types of human cancer, reduced LDHB and hnRNPF expressions were observedboth at the mRNA and protein levels in MCC-2 and MCC-3 cells following mTOR pathway inhibition, indicating that LDHB and hnRNPF are downstream effectors of mTOR pathway." (PMID 25284964, 2013). "It is believed that the lack of potent efficacy by rapamycin in cancer patients may result from activation of Akt signaling following chronic mTOR inhibition." (PMID 24379984, 2013). "Taken together, these studies suggest an important role for the microenvironment in the response of stem cells (including cancer stem cells) to CR or CR mimetics targeting the mTOR pathway, and this will no doubt be an important and exciting research area in the coming years." (PMID 24280167, 2013). "The novel ATP-competitive mTOR inhibitors (e. g., Torin1, PP242, ku-0063794, and WAY-600), which inhibit both mTORC1 and mTORC2, exert marked effects on protein synthesis, cell growth, and cell proliferation, and strongly promote autophagy in various cancer cell types in vitro." (PMID 23874880, 2013). "This idea is supported by our observations that downregulation of Rictor suppressed tumorigenicity of cancer cells without any effects on normal cells, whereas downregulation of either Raptor, a component of mTORC1, or mTOR itself strongly suppressed the growth of normal cells." (PMID 24244675, 2013). "In other words, inhibition of mTOR may reduce cancer through other mechanisms which are not considered in this study, but does drive cancer progression through elevating pAKT levels and driving uncontrolled cell proliferation." (PMID 24400038, 2013).
cancer (continued). "When looking at nine canonical signaling pathways (PI3K/AKT/mTOR, MAPK, TGF-B, p38/MAPK, JNK, JAK/STAT, WNT/β-Catenin, and NFκB) and copy number variation in terms of patient survival, the PI3K/AKT/mTOR pathway was the most frequently altered cancer related pathway." (PMID 23591839, 2013). "In addition, mTOR inhibitors have shown further anti-cancer properties with promising results in the treatment of nontransplant patients with B-cell lymphomas and have been trialled in the treatment of relapsed mantle cell lymphoma." (PMID 24565283, 2013). "Just like redox disruptors, a surprising number of “targeted” drugs in advanced stages of clinical testing, including proteasome, MAPK, and mTOR inhibitors, target molecules that are essential to the survival of normal cells and thus not per se cancer cell selective." (PMID 23902736, 2013). "Consequently, the identification of negative feedback loops by either allosteric or active-site mTOR inhibitors has emerged as an area of major interest in cancer therapy." (PMID 23437362, 2013). "Thus to achieve effective suppression of cancer growth in some situations, it maybe be important to combine PI3K/mTOR inhibitors with pan PI3K inhibitors." (PMID 23085539, 2012). "In the present study, we demonstrate that human and canine cancer cell lines express constitutively activated class I PI3K/Akt/mTORC1 axis signaling, as evidenced by detectable levels of phosphorylated forms of PI3K downstream effectors, including Akt, mTOR, S6RP, 4EBP1 and eIF4E." (PMID 22647622, 2012). "It is intriguing to speculate that cancers with Nrf2 pathway activation may be vulnerable to coordinate mTOR and autophagy inhibition and RIPK- and ROS-mediated necroptosis, and that inactivation of RIPKs and necroptosis is a mechanism of resistance to cancer therapy." (PMID 22848625, 2012). "Metastatic sarcoma : The serine/threonine kinase, mammalian target of rapamycin (mTOR), is a protein kinase of the phosphatidylinositol 3-kinase (PI3K)/AKT signaling pathway thought to have a key role in controlling cancer growth and thus is an important target for cancer therapy." (PMID 22709827, 2012). "Hence, mTOR influences tumor growth by playing a global role that is not restricted to cancer cell proliferation and survival but that also affects the angiogenic and the immunological responses found in the microenvironment of a tumor." (PMID 24212820, 2011). "mTOR is a key integrator of growth factor and nutrient signals and is a critical mediator of the phosphatidylinositol-3-kinase/protein kinase B/Akt (PI3K/PKB/Akt) signaling pathway, which is one of the most frequently deregulated molecular networks in human cancer." (PMID 21470407, 2011). "In summary, the current study has demonstrated that the combination of RAD001 and the PI3K/mTOR inhibitor BEZ235 exhibits synergistic inhibition on the growth of NSCLC cells in vitro and in vivo and thus represents a novel strategy to enhance the efficacy of mTOR-targeted cancer therapy." (PMID 21695126, 2011). "Aktis activated by mTOR inhibition but does not account for cell protection Whilein most cancer-related models the mTOR cascade exerts antiapoptotic functionsdownstream of the PI3 kinase/AkT PKB signaling axis, few examples of cellprotection by inhibition of mTOR/S6K have been reported." (PMID 20739737, 2010).
cancer (continued). "IGF system dysregulation/overactivation resulting from receptor and ligand abnormal expression may favor cancer progression by various mechanisms that depend on the constitutive activation of the two main branches of intracellular signaling, the PI3K/mTOR and the ERK1/2 signaling pathways." (PMID 19609453, 2009). "Since mTOR+/kd mice are indistinguishable from wild type in phenotypes, further studies involving conditional tissue-specific inactivation of mTOR will be necessary to clarify the role of mTOR in immune system and in diseases such as cancer." (PMID 19457267, 2009). "Moreover, continued activation of PI3K/Akt signalling, which triggers mTOR, seems to contribute to the development and maintenance of an EGFR-resistant phenotype, and it has been found in tumour samples from cancers patients failed in EGFR-targeted therapy." (PMID 18319715, 2008). "Cancer cells in this tumour are negative for phospho-Akt, but show positive cytoplasmic expression for activated phospho-mTOR and positive nuclear phosphorylated expression for the downstream mTOR effector, p70S6k." (PMID 17726467, 2007). "Furthermore, rapamycin’s therapeutic effect is mostly confined to the mTOR pathway, which may not be sufficient in cancers with complex and redundant signaling networks." (PMID 39762538, 2025). "Cavazzoni and colleagues also reported in cancers of unknown primary with FGFR2 amplification that the combination of infigratinib and trametinib was synergistic and reduced the activity of both the AKT/mTOR/p70S6K and the MAPK pathway beyond the effects of the monotherapies." (PMID 40415599, 2025). "This hyperactivation of the Akt/mTOR pathway in the absence of MLIP suggests that MLIP deficiency may accelerate aging in cells and may heighten their susceptibility to tumor development, potentially implicating MLIP in cancer biology." (PMID 38994962, 2024). "However, cancer cells display much higher ROS levels than normal cells due to dysfunctional mitochondria, oncogene activation and antioxidant imbalance; for instance, ROS inactivate PTEN facilitating PI3K, Akt/mTOR signaling, which ultimately leads to tumor progression." (PMID 37298798, 2023). "Therefore, we can only infer that promoting DNAPK expression through hsa_circ_0136666 has a relatively small impact on Akt, and hsa_circ_0136666 may not promote cancer development through the Akt/mTOR pathway." (PMID 38093288, 2023). "Similarly, the expression of the NORAD was notably increased in cancer tissues and cells compared with that in normal tissues and cells in NSCLC, which regulates the proliferation, migration, and invasion capabilities of NSCLC cells by targeting the miR-520a-3p/PI3k/Akt/mTOR signaling pathways." (PMID 36793900, 2023). "The inhibition of mTOR may have antiproliferative effects with several mechanisms including a selective decrease in the translation of mRNAs (such as c‐myc, VEGF) essential to tumorigenesis and a decreased phosphorylation of cyclin D1 leading to cycle progression arrest in cancer cells." (PMID 36205189, 2023). "In contrast, primary tissue-derived human CD44+ EpCAM+ ALDH1high ERα− cancer stem cells showed an abrogation by mTOR inhibitors during combination treatment with tamoxifen, which failed to prevent sphere formation alone until an mTOR inhibitor was introduced alongside it." (PMID 37904250, 2023).